ELAVL2 (ELAV like RNA binding protein 2)
Diseases named in the same sentence as ELAVL2 in open-access papers (continued):
Sharing a sentence is not in itself a finding about the gene and the disease.
tumor (16 papers, 2012 to 2025). "ELAVL2 expression level was found to be dramatically lower in GBM than that in non-tumor tissues, supporting the previous observation that ELAVL2 deletion is a characteristic of GBM." (PMID 38548861, 2024). "As a result, we selected 13 candidate target genes whose mRNA expression levels were strongly correlated with ELAVL2, thereby implicating these genes as potential downstream effectors of ELAVL2-mediated tumor suppression." (PMID 38548861, 2024). "In conclusion, we identified ELAVL2 as a potential tumor suppressor in GBM by regulating the mRNA stability of EMT-inhibitory molecules." (PMID 38548861, 2024). "Since both BASP1 and REPS2 have been shown to possess tumor-suppressive activities, it will be worthy of further investigation to decipher their potential signaling network with ELAVL2." (PMID 38548861, 2024). "Our study found that the expression of ELAVL1 was significantly high in tumor samples, while that of other three members (ELAVL2, ELAVL3 and ELAVL4) was significantly low in tumors." (PMID 28035070, 2017). "ELAVL2 is located on chr9p21, and along with chr10 loss, chr9p deletion has been considered one of the most frequent genomic alterations in GBM, implying the presence of potential tumor suppressors on these deleted chromosomal segments." (PMID 38548861, 2024). "To identify potential downstream regulatory factors responsible for mediating the tumor-suppressive effect of ELAVL2, we conducted gene correlation analyses across three independent datasets (TCGA, GSE16011, and GSE53733) using a stringent cutoff of correlation p-value ≤ 10-4." (PMID 38548861, 2024). "Interestingly, in contrast to the tumor suppressive role of ELAVL2 observed in our study, tumor promoting effects of ELAVL2 have also been reported." (PMID 38548861, 2024). "However, as ELAVL2/HuB interacts with HuR to form a complex within the cytosol of tumour cells, it is likely that ELAVL2/HuB is indirectly degraded in complex with HuR, or that they mutually stabilise each other." (PMID 37925433, 2023). "For instance, ELAVL2, which encodes RNA-binding protein specific to the nervous system, was highly biased towards underexpression among tumor samples regardless of the copy number status." (PMID 23408991, 2013). "In contrast, the expression of ELAVL2, RAD9B and CNOT3, already identified as tumor suppressor, and inhibitors of cell cycle progression, respectively, were upregulated by the miR-Combo." (PMID 37749143, 2023). "ELAVL2 is located at the chromosome band 9p21.3, where CDKN2A (a well-known tumor suppressor) is also located." (PMID 28035070, 2017).
cancer (14 papers, 2012 to 2025). A tumor composed of atypical neoplastic, often pleomorphic cells that invade other tissues. "We found that ELAVL2 is most frequently deleted in GBM compared to other cancers and associated with distinct clinical and molecular features." (PMID 38548861, 2024). "Such contradictory roles of ELAVL2 underpin its functional plasticity that makes ELAVL2 a “Swiss-Knife” gene whose function is selectively regulated in a tissue- and cancer-specific manner." (PMID 38548861, 2024). "We then sought to determine if ELAVL2 deletion specifically occurs in GBM compared to other types of cancer." (PMID 38548861, 2024). "The result showed that the transcript level of ELAVL2 in GBM cell lines is reduced compared to that of other cancer cell lines." (PMID 38548861, 2024). "The alteration frequency of ELAVL2 in various cancer datasets was ranked, and the result showed that ELAVL2 was deleted at the highest level in GBM compared to other cancers, suggesting that ELAVL2 deletion is one of the frequent genomic alterations in GBM." (PMID 38548861, 2024). "However, the role of ELAVL2 in human cancer development remained elusive." (PMID 38548861, 2024). "The analysis revealed that gene sets indicative of invasiveness of cancer, including TNFα signaling via NF-kB, EMT, and hypoxia, are upregulated in ELAVL2-low GBM patients." (PMID 38548861, 2024). "When cancer type was restricted to only GBM samples, ELAVL2 was also found to be deleted the most (19%) compared to other ELAVL members." (PMID 38548861, 2024). "While RBFOX3, RBM11 (RNA binding motif protein 11) and DDX25 (DEAD-box helicase 25) are generally downregulated in cancers compared to normal cells, the dysregulation of CELF5, ELAVL2 and ESRP1 is dependant on the type of cancer." (PMID 30704403, 2019). "Finally, there is enough information on the role of CDKN2A, ZIC2, ELAVL2, and HS6ST2 genes in cancer." (PMID 40361484, 2025). "In GBM scenario, we hypothesize that downregulation of ELAVL2, ELAVL3 and ELAVL4 may be preferred to further enhance the translation of HuR, leading to a less differentiated and highly proliferative state of cancer cells." (PMID 28035070, 2017).
neurodevelopmental disorder (4 papers, 2021 to 2025). A behavioral and cognitive disorder with onset during the developmental period that involves impaired or aberrant development of intellectual, motor, or social functions. "Given the established link between ELAVL proteins and brain development, ELAVL2 regulation was studied as a pathway of interest in neurodevelopmental disorders." (PMID 37697079, 2023). "Co-expression networks for ELAVL2 highlight its connection to neurodevelopmental genes, implying it to be a potential important gene for neurodevelopmental disorders more general." (PMID 34054130, 2021).
neurodegenerative disease (2 papers, 2023 to 2024). A disorder of the central nervous system characterized by gradual and progressive loss of neural tissue and neurologic function. "Among the target genes of these miRNAs, we found five upregulated genes in our snRNA-seq dataset are associated with neurodegenerative diseases, including Atcb, Elavl2, and Fgf1, which are associated with ALS." (PMID 38467605, 2024).
neurological diseases (2 papers, 2014 to 2025). "Numerous splicing factors identified here have been reported to have functions in neuronal differentiation, neurological diseases, or synaptic plasticity, such as ELAVL2, ZIC1, A2BP1 (official gene symbol Rbfox1), and FUS." (PMID 24758366, 2014).
brain disorder (1 paper, 2025). A disease affecting the brain or part of the brain. "Another is Elavl2, a member of the ELAVL family of RNA-binding proteins, which regulate posttranscriptional processes, such as neuronal mRNA stability and splicing, and are implicated in neural development and brain disorders." (PMID 39633007, 2025).
psychiatric diseases (1 paper, 2011). "Given their role in neuronal differentiation and plasticity, nELAVL proteins including ELAVL2 could be potential candidates for neurodegenerative and psychiatric diseases." (PMID 21674006, 2011).
ELAVL2 also shares sentences with these, for which no sentence is quoted: infection (4 papers); neuroblastoma (3); amyotrophic lateral sclerosis (2); gastric cancer (2); glioblastoma (2); hepatocellular carcinoma (2); pancreatic cancer (2); anaplastic ependymoma (1); Arthritis (1); B-cell lymphoma (1); cerebellar ataxia (1); colorectal adenocarcinoma (1); congenital cataracts (1); depression (1); diabetes (1); diabetic neuropathy (1); endometriosis (1); epilepsy (1); fibrosis (1); hydatid disease (1); Hypertension (1); influenza (1); iritis (1); laryngeal disease (1); liver cancer (1); lung adenocarcinoma (1); lymphoma (1); melanoma (1); myeloma (1); non-small cell lung carcinoma (1).
A further 9 diseases each share a sentence with ELAVL2 in 1 paper.